IL10 (interleukin 10)
Diseases named in the same sentence as IL10 in open-access papers (continued):
Sharing a sentence is not in itself a finding about the gene and the disease.
dengue (continued). "In our earlier studies we found that serum IL-10 levels were associated with severe dengue." (PMID 25366086, 2014). "Therefore, although IL-10 is associated with T cell apoptosis, it appears that both are markers of severe dengue possibly independently associated with each other." (PMID 23209731, 2012). "In addition, Th2 cytokines such as IL-10 have been associated with increased severity in dengue patients." (PMID 21695193, 2011). "Type 2 cytokines such as IL-13 and IL-10 have been implicated in the pathogenesis of severe dengue." (PMID 18060049, 2007). "Additionally, a close association between cytokine imbalance and SOCS1/3 observed in patients with a severe dengue infection suggested that the combined analysis of SOCS1/3, IL-10, and IL-6 expression levels could identify at-risk patients for severe dengue." (PMID 32120897, 2020). "However, most severe dengue patients had lower levels of interferons and Th1 cytokines and increased levels of secreted factors such as IL-6, IL-8 and IL-10 that could potentially cause leakage in blood capillaries." (PMID 26982706, 2016). "Thus, IL-10 may cause lymphocyte dysfunction through the suppression of the T cell proliferative response to mitogens, which occurs in dengue patients during the early stages of infection." (PMID 23800014, 2013). "Increased IL-10 production has also been highly proposed as a mechanism of silencing immune activation in ADE conditions or individuals with severe dengue." (PMID 39902963, 2025). "Between the two types of ADE, intrinsic ADE plays a greater role in elevating dengue replication by inhibition of type 1 interferon and activation of interleukin-10 (IL-10) biosynthesis, whilst extrinsic ADE helps to facilitate virus entry." (PMID 41009534, 2025). "Key cytokines such as interferon-gamma (IFN-γ), tumor necrosis factor (TNF)-α, and interleukin (IL)-10 are pivotal in the pathogenesis of dengue." (PMID 38910682, 2024). "Levels of IL-10 and IFN-γ, which have previously been shown to be produced by CD4+ T cells and linked to dengue disease, also appeared correlated with each other." (PMID 39088280, 2024). "Recent studies have suggested IFN-γ, IL-10, GM-CSF, and MIP-1β as potential predictor for severity of dengue disease and IL-10 as a diagnostic marker for dengue fever." (PMID 37235332, 2023). "We showed that IFN-α, IFN-γ, TNF-α, IL-6, MCP-1, IL-2, IL-4, and IL-10 production was higher in patients with dengue than in those with AFI." (PMID 38003826, 2023). "Between mild and severe dengue groups, IL-10 levels were significantly elevated in severe dengue, both in plasma and EVs." (PMID 37982662, 2023). "The results from individuals with previous Zika infection (DV-ZV+) were comparable to those in previously dengue-naive individuals, except for IL-10 and IL-17A (which were elevated in patients with previous Zika infection)." (PMID 37943879, 2023). "Nevertheless, a Th2 profile leads to the secretion of cytokines, such as IL-4, IL-10, and IL-13, which stimulate B cells to secrete antibodies and are more frequent in dengue patients presenting hemorrhagic disease." (PMID 38003826, 2023). "Matching with previous reports, patients with severe dengue exhibited an increased level of IL-10 compared to the levels in patients with mild disease." (PMID 35631079, 2022). "Even so, only IL-10 distinguished mild to moderate cases of dengue, which would indicate its role in helping the clinical prognosis." (PMID 35631030, 2022). "In this way, we suggest that IL-10, even in mild to moderate cases of dengue, is a marker that should be investigated to help the clinical prognosis." (PMID 35631030, 2022). "IL-10 levels were significantly higher in dengue groups compared to healthy donors and, still, IL-10 differentiate DF from DFWS/Sev patients." (PMID 35631030, 2022).
dengue (continued). "Both the Treg cells and Th2 cells secrete IL-10 and TGF-β, causing a disturbance in the fine balance of different cytokines ultimately leading to ‘cytokine storm’ and severe dengue disease." (PMID 33231723, 2021). "Elevated IL-10 levels in sera of severe dengue patients, leads to T cell apoptosis resulting in reduced viral clearance and impaired antiviral response." (PMID 33231723, 2021). "In the present study, the dengue patients with thrombocytopenia had significantly higher levels of IL-10." (PMID 34578370, 2021). "In dengue severity, Th1 cytokines GM-CSF and IFNγ antagonize Th2 cytokines IL-10 and IL-4, respectively, for the progression towards DHF/DSS." (PMID 34447698, 2021). "Within dengue severity IL-1β, IL-10 (Th1/2), and IP-10 (Th1) have been upregulated in DHF/DSS than DF, and IL-6 (Th1/Th2) and IL-17A (Th17) in DHF than DSS." (PMID 34447698, 2021). "For example, dengue virus infection was reported to drive IL-10-mediated SOCS3 expression and the consequent inactivation of JAK/STAT pathways." (PMID 32120897, 2020). "The cytokines IL-1β, CXCL8, and IL-10, released by monocytes in response to interactions with platelets from dengue patients, are frequently observed to be increased in plasma of severe dengue patients." (PMID 33102253, 2020). "Lethal dengue disease is characterized by the robust induction of cytokines and chemokines in mouse serum, such as interleukin (IL)-6, IL-10, and interferon (IFN)-γ, showing a high correlation with infectious disease progression." (PMID 33072626, 2020). "Higher concentrations of cytokines such as IFN-γ, TNF-α and IL-10 were observed in the sera of patients with severe dengue in Cuba, India and Vietnam." (PMID 32751561, 2020). "In this concern, it is important to note that an increase in IL-10 was found in dengue patients; this anti-inflammatory cytokine is produced late in infection, has immunosuppressive functions, and is associated with greater severity of infection." (PMID 30901375, 2019). "While similar observations have been made by others for IFN-γ and IL-10 in severe dengue, increased levels of GM-CSF and MIP-1β novel to the present study." (PMID 30626045, 2019). "Increased plasma cytokine levels of IFN-γ, MIP-1β, GM-CSF and IL-10 and (p = 0.02, 0.0004, 0.03, 0.034) significantly differentiated severe dengue cases from patients with dengue fever in the cohort studied by us." (PMID 30626045, 2019). "A significant increase in IL-10 levels from dengue patients was observed in comparison to healthy controls (p< 0.0001)." (PMID 30901375, 2019). "Patients with secondary DENV2 infections exhibited significantly higher IL-10 levels in a study on 182 patients hospitalized with dengue in Taiwan." (PMID 29740424, 2018). "This study is an attempt to build a mathematical model, to address the combined effect of cytokines and immune mediators S1P, IL-1β, TNF-α, PAF and IL-10, and determine the severity of dengue at an early stage." (PMID 28284213, 2017). "Serum concentrations of IL-2, IL-4, IL-6, IFN-γ, TNF-α, IL-17, and IL-10 were determined in dengue patients at 6 or 7 days of fever onset and were compared with values obtained in a group of healthy controls." (PMID 28827898, 2017). "For example, studies have shown that tumor necrosis factor α (TNF-α), IL-8 and IL-10 levels are higher in patients with severe dengue versus mild dengue fever." (PMID 28644404, 2017). "In agreement, simultaneous increase of IL-6 and IL-10 in DHF is indicative of the dysregulated immune response that leads to the progress of dengue severity." (PMID 28827898, 2017). "Diverse single nucleotide polymorphisms (SNPs) in genes such as HLA-I, HLA-II, TNF-α, IL-10, TGF-β1, FcγRIIa, VDR, CD209 and OAS have been associated with symptomatic dengue or considered protective against the disease, in Asian and Latin American populations." (PMID 28241052, 2017).
dengue (continued). "Even the immune system genes associated with dengue illness, such as TNF-α, IL-10, TGF-β1, FcγRIIa and CD209, can also be related with the RXRA gene in several pathways, as their expression is controlled by dimers formed by RXRA and other nuclear factors." (PMID 28241052, 2017). "IL-10 concentration was higher in dengue patients than in the control group (112.2 ± 26.97 pg/ml versus 59.58 ± 26.03 pg/ml, resp.; P < 0.001)." (PMID 28827898, 2017). "Another recent report revealed that, in fact, a disturbance in the balance between inflammatory (IL-6 and IL-8) and anti-inflammatory (IL-10) cytokines, would characterize possible mechanisms related to the occurrence of hemorrhagic manifestations in dengue." (PMID 28006034, 2016). "By both univariate and multivariate analysis, we show that the most prominent features of severe dengue are lower type I and type II interferons, IL-7, sCD40L and increased production of IL-6, IL-8, IL-10 and VEGF." (PMID 26982706, 2016). "CD14+ monocytes were the major contributors of IL-10 transcript further confirming the role of monocytes in the pathogenesis of dengue disease." (PMID 26982706, 2016). "As expected, we observed over 10-fold increase in IL-10 mRNA levels in dengue samples as compared to healthy control." (PMID 26982706, 2016). "Various viruses utilize IL-10 as a viral evasion mechanism including classical swine fever, porcine reproductive and respiratory syndrome virus, dengue, and West Nile virus." (PMID 27008425, 2016). "It is likely that the dynamic regulation of IL-10 levels at different stages of the disease involving different cell types determines the course of dengue disease." (PMID 26982706, 2016). "Severe dengue cases had low Th1 cytokines and a concurrent increase in the inflammatory mediators such as IL-6, IL-8 and IL-10." (PMID 26982706, 2016). "In this study, the expression profile of several important inflammation mediators, including TNF-α, IL-1α, IL-1, IFN-γ and IL-10, was investigated in dengue patients at different time points." (PMID 27301555, 2016). "Although clinical studies have shown that the increased levels of IL-10 can be detected and show impact on dengue disease statement." (PMID 25412261, 2014). "The time-kinetic analysis shows increased levels of IL-10 from the onset of fever to defervescence, and viremia primarily occurs during fever in dengue patients." (PMID 23800014, 2013). "IL-10 levels were significantly higher (p = 0.01) in those with primary dengue (mean 363, SD ± 923.6 pg/ml) than those with secondary dengue (mean 161.1, SD ± 298.6 pg/ml)." (PMID 23883139, 2013). "A recent study in 52 patients with acute dengue infection (which included 3 patients with severe dengue) has shown that serum IL-10 levels along with platelet counts were two of the most important parameters associated with DHF." (PMID 23883139, 2013). "When using the IL-10 cut-off value as 115.8 pg/ml (mean + 2SD of the serum IL-10 values in healthy controls), the odds ratio of developing severe dengue was 2.77 (95% CI 1.386 to 5.520)." (PMID 23883139, 2013). "They found that MIP-1β and IP-10 levels were overall higher in the febrile and critical phases of dengue and serum IL-10 levels remained unchanged in patients with dengue with warning signs, whereas levels decreased in those without warning signs." (PMID 23883139, 2013). "As dengue is a very dynamic disease, we determined serum IL-10 levels and MIF levels in 65 patients during the febrile phase and critical phase, hoping to gain a better insight into how these cytokines change in patients with SD and non SD." (PMID 23883139, 2013). "In our earlier studies we found that IL-10 levels in the unstimulated ELISpot culture supernatants were higher in patients with severe dengue when compared to those with non severe dengue." (PMID 24040431, 2013).
dengue (continued). "We feel that the wide range of IL-10 and other cytokines seen in patients with severe dengue and milder forms of dengue is due to the complex nature of this disease." (PMID 23883139, 2013). "The role of IL-10 in DENV disease is still contradictory as it has been correlated with severe dengue disease, despite having multiple regulatory functions that aid in DENV clearance." (PMID 22816004, 2012). "Taken together our data suggests that the two immunosuppressive cytokines IL-10 and TGFß, possibly play different roles in the pathogenesis of dengue." (PMID 23209731, 2012). "Proinflammatory cytokines namely interleukin-8 (IL-8), tumor necrosis factor-α and interferon-γ and anti inflammatory cytokine IL-10 also contribute to dengue disease pathogenesis." (PMID 22559908, 2012). "Using an 8-color flow cytometry panel, we then measured the number of CD3+ CD4+ or CD3+ CD8+ T cells producing cytokines that have been implicated in natural dengue disease: IFNγ, TNFα, IL2, and IL10." (PMID 22816004, 2012). "The IL-10 profile in dengue patients showed low levels in dengue fever cases, while increased levels were observed in DHF patients." (PMID 21695193, 2011). "Cytokines that are undetectable in the blood of healthy individuals are elevated in dengue-infected patients, such as IL-1β, IL-2, IL-6, IL-8, IL-10, IL-13, IL-18, IFNγ, TNFα, and MCP1." (PMID 21206915, 2010). "The anti-inflammatory cytokine IL-10 has also been reported as having higher levels in DHF/DSS patients than patients with dengue fever." (PMID 21206915, 2010). "In dengue patients, circulating EVs contribute to immune dysregulation by transporting immunosuppressive molecules, including checkpoint inhibitors such as PD-L1 and anti-inflammatory cytokines like IL-6 and IL-10." (PMID 40573398, 2025). "This study demonstrated that the Th2-biased cytokine storm pattern observed in hTim4 mice with DENV-2 infection, characterized by elevated levels of Il6 (**P = 0.0082), Il9 (P = 0.3965), Il10 (*P = 0.0168), was highly consistent with the serum profiles of clinical dengue fever patients." (PMID 40623122, 2025). "Moreover, high serum levels of TNF-α, IL-1β, IL-6, CXCL-8/IL-8, and IL-10 correlated with severity of the disease in dengue patients, showing a preponderant role of NF-kB-dependent inflammatory response in dengue immunopathogenesis." (PMID 40934228, 2025). "Nevertheless, sustained IFN-γ expression, together with increased Kupffer cells and IL-10 (most pronounced during the early phase of infection), suggests a predominantly Th1 immune profile in the liver, consistent with observations in human dengue patients." (PMID 41472288, 2025). "This corresponds to elevated levels of IL-10 and reduced IFN levels in severe dengue patients (DENV-2/3), suggesting a close association between Th2-type cytokines and the severity of dengue virus infection." (PMID 39312399, 2024). "These two clusters, which differed on IL-10 expression levels did not associate with past dengue disease severity." (PMID 39232783, 2024). "We found that Tregs from severe dengue patients produced higher amounts of IL-10 after PMA/ionomycin stimulation, a cytokine that has been implicated in dengue immunopathogenesis and which can be found at increased concentrations in patients with severe dengue (9, 10, 66, –, 68)." (PMID 38752787, 2024). "Interestingly, Tregs from severe dengue patients produce more interleukin-10 after in vitro stimulation compared to Tregs from classical dengue fever patients." (PMID 38752787, 2024). "In contrast, during convalescent DENV infection, the mean levels of IFN-γ, CXCL10, IL-4, and IL-10 remained relatively high, suggesting that the sustained interplay of Th1, Th2, and Treg may be needed for dengue control in this setting." (PMID 37235332, 2023). "In dengue, IL-10 levels in early illness were an important predictor of developing severe disease." (PMID 35786403, 2022).
dengue (continued). "Extrapolating for our data, quantitatively, the set IL-10/IFN-γ could contribute to vascular leakage in the severe forms of dengue." (PMID 35631030, 2022). "A recent study compared the levels of cytokines in the acute phase of dengue and COVID-19, and found high levels of several cytokines throughout the course of these diseases, including high levels of immunosuppressive cytokines such as IL-10." (PMID 35212704, 2022). "Supportive data from India that IL-10 is predictive of mortality in children with dengue." (PMID 33495264, 2021). "Experimental dengue viral infection shows increase of IL-10 facilitates dengue replication." (PMID 34447698, 2021). "Higher NS1 levels, which are associated with milder forms of dengue also correlated directly with high levels of IFN-γ from CD56+CD3+ NKT cells, TNF-α from CD16+ monocytes and IL-10 from granulocytes, suggesting a requirement for high viral antigen levels to achieve efficient innate cell activation." (PMID 34335578, 2021). "Additionally, the dengue patients with thrombocytopenia (<100,000/mm3) had significantly higher levels of IL-10 (median = 4.0 pg/mL; IQR: 2.4–9.3; p = 0.008) compared to those with platelet counts ≥100,000/mm3." (PMID 34578370, 2021). "Furthermore, in our study on B cell responses in dengue patients, we observed higher frequencies of CD19+CD24hiCD38hi B cells, which are known to produce IL-10, in patients with mild dengue compared to those with severe dengue." (PMID 34293057, 2021). "The deregulation of IL-10–producing cells in dengue may thus contribute to the excessive inflammatory response observed during acute dengue infection." (PMID 34293057, 2021). "Studies also suggest that manipulating IL-10, an anti-inflammatory cytokine may serve as an effective antiviral treatment in addition to the development of a safe dengue vaccine." (PMID 33102253, 2020). "Targeting senescence and IL-10 may diminish DENV-susceptible monocytes and may be an approach for future anti-dengue therapy." (PMID 32850477, 2020). "As IL-10 was found to be a key cytokine elevated during early illness during acute dengue, we compared the usefulness of IL-10 in predicting those who are likely to develop DHF, along with other key cytokines such as IL-6, TNFα and IL-1β, which cause vascular leak." (PMID 33199778, 2020). "Generally, TNF-α, as well as IL-4, IL-6, IL-8, and IL-10, are increased in dengue patients." (PMID 33072626, 2020). "Moreover, a decrease in the expression of the inflammasome-related genes NLRP1, NLRC4, caspase-1, IL-1β and IL-18 was observed, as well as an increase in serum levels of C-reactive protein and IL-10 in dengue patients versus healthy donors." (PMID 30901375, 2019). "Besides decreased percentages of CD24hiCD38hi transitional B cells/Bregs and CD27− naïve B cells in severe dengue infection, we also demonstrate here the inability of B cells isolated from dengue patients to produce IL-10 and TNF-α upon TLR/CD40 stimulation." (PMID 31736948, 2019). "Elevated IL-10 has been a consistent finding in patients with severe dengue." (PMID 28827898, 2017). "Additionally, IL-10 has also been interpreted as a marker of disease progression in severe dengue cases." (PMID 28006034, 2016). "However, the IL-10 levels reported in the current study were lower than those commonly reported in the literature during symptomatic/severe dengue." (PMID 27459266, 2016). "Severe dengue has been proposed to be an outcome of exaggerated immune response and pathology resulting from the onslaught of inflammatory mediators such as IL-6, IL-8, IL-10 and TNF-α." (PMID 26982706, 2016). "First, IL-10 may be a useful prognostic tool because IL-10 serum levels are positively correlated with dengue disease severity, particularly in DHF/DSS patients, and because IL-10 displays immunosuppressive properties during DENV infection." (PMID 25412261, 2014).